CXCL1 (C-X-C motif chemokine ligand 1)
Diseases named in the same sentence as CXCL1 in open-access papers (continued):
Sharing a sentence is not in itself a finding about the gene and the disease.
tumor (continued). "CXCL1 shows increased expression in the BC tumor stroma and its plasma levels have been linked to the number of circulating tumor cells." (PMID 36431173, 2022). "For instance, necroptosis-mediated dying tumor cells induce the C-X-C motif chemokine ligand 1 (CXCL1) and sin3A-associated protein 130 (SAP130) release to aggravate inhibitory TIME." (PMID 36466844, 2022). "Elevated levels of CXCL1 in CRC were associated with tumor size, progression, depth of invasion, and patient survival." (PMID 36581948, 2022). "In the mouse tumor tissues, Trim11 deficiency also upregulates the expression of Cxcl1, Cxcl2 and Cxcl3." (PMID 36192394, 2022). "C-X-C motif chemokine ligand 1 (CXCL1) is the most abundant chemokine secreted by tumor associated macrophages, which is located on chromosome 4." (PMID 36581948, 2022). "Tumor-derived CXCL1 was reported to boost NSCLC cell proliferation by recruitment of tumor-associated neutrophils." (PMID 35719962, 2022). "For example, primary CRC tumor-secreted VEGF-A stimulated tumor-associated macrophages to produce CXCL1, which recruited CXCR2-positive myeloid-derived suppressor cells (MDSCs) accumulated in the pre-metastatic site and facilitated liver metastasis." (PMID 36348319, 2022). "C‐X‐C motif chemokine ligand 1 (CXCL1) is associated with increased cell transformation, tumor growth, and invasive potential." (PMID 34995016, 2022). "If a tumor cell from the blood stops in bone tissue, it causes bone remodeling by secreting CXCL1 and hence bone metastasis." (PMID 35457023, 2022). "HIFU constructed an inflammatory TME with concentration gradients of the chemokines CXCL1/KC and IL-10, which was attributable to the proinflammatory response caused by the necrosis of tumor cells and the release of necrotic debris." (PMID 34715854, 2021). "Tumor cell-triggered increased production of CXCL1 by tumor-associated macrophages resulted in increased myeloid cell recruitment to the premetastatic liver tissue." (PMID 34868988, 2021). "CXCL1,2,3 chemokines are also involved in recruiting immune cells such as myeloid cells and tumor-associated neutrophils to the tumor microenvironment and have been associated with increased tumor survival and metastasis." (PMID 34183723, 2021). "More specifically, the activation of NF-kB in tumor cells enhances the expression of several genes (including Ccl7, Cxcl1, Ccl5, Slc39a10, Lcn2, Zc3h12a, and Enpp2) that are implicated in tumor migration, angiogenesis, and formation of pre-metastatic niches." (PMID 33567747, 2021). "The involvement of tumour-associated dendritic cells (TADCs) and their soluble factor CXCL1 on colon cancer cells was investigated." (PMID 34572431, 2021). "Higher levels of CXCL1 are associated with tumor size, advancing stage, depth of invasion, and patient survival in liver metastasis of colorectal and hepatocellular cancer." (PMID 33466892, 2021). "For example, CXCL1 together with its receptor CXCR2 were implicated in assisting with the homing of neutrophils into the tumor microenvironment in OS." (PMID 34225733, 2021). "Signaling of CXCR2 and its ligands (CXCL8 and CXCL1) leads to the recruitment of tumor-promoting immune cells, such as tumor-associated macrophages and MDSCs." (PMID 34944871, 2021). "VEGF secreted by cells in the tumor niche causes an increase in CXCL1 and CXCL8 expressions in endothelial cells, in a process important to angiogenesis and the migration of cancer cells." (PMID 33467722, 2021). "In this regard, tumor-derived CXCL1, a ligand for CXCR2, has been implicated as a mechanism of resistance to CD40 immunotherapy." (PMID 33497362, 2021). "Consistently, due to the tumor-promoting effects, high CXCL1 expression has been shown to be a risk factor for cancer prognosis, with poor OS, advanced tumor, node, and metastasis stage, and lymph node metastasis." (PMID 31991604, 2020).
tumor (continued). "C-X-C motif chemokine ligand 1 (CXCL1) is a chemokine secreted by macrophages whose expression in the tumor stroma is associated with poor prognosis and BC metastasis." (PMID 33371274, 2020). "Increased levels of CXCL1 are associated with tumor size, advancing stage, depth of invasion, and patient survival." (PMID 32079335, 2020). "By activating CXCR2, CXCL1 is associated with cancer cell growth and proliferation, tumor angiogenesis and metastasis." (PMID 32326946, 2020). "Interleukin 8 (CXCL8), CXCL3, and CXCL1 are CXC chemokines that are strongly associated with tumor angiogenesis." (PMID 32462020, 2020). "Our study supports existing data that tumor-associated macrophages (TAMs) play a vital role in CXCL1-induced cancer progression." (PMID 33256011, 2020). "In summary, biomarkers associated with both oncogenic (ITGAV, CEACAM1, CXCL1, IL-10RB) and tumor-suppressive actions (CEACAM1) were found to increase the diagnostic performance of HE4, CA125 and age in our study." (PMID 33075095, 2020). "Tumor associated macrophages (TAMs)-secreted CXCL1 was demonstrated to recruit CXCR2+ myeloid suppressor cells (MDSCs) to promote liver PMN formation in a colorectal cancer xenograft." (PMID 32213179, 2020). "CCL20 and CXCL1 are chemokines mediated by cancer cells or other immune cells in the tumor microenvironment and are associated with the differentiation and progression of ccRCC." (PMID 31747386, 2019). "SMAD4-deficient CRC cells also produce C-X-C motif chemokine ligand CXCL1/8 to recruit its corresponding receptor CXCR2+ tumor-associated neutrophils (TAN)." (PMID 31756952, 2019). "CXCL1 is upregulated in various cancers and associated with cancer progression, such as cancer cell growth, proliferation, tumor angiogenesis and metastasis, after the activation of CXCR2." (PMID 30115896, 2018). "CXCL-1 was also found to be a cytokine secreted by tumor-associated macrophage, which recruits myeloid-derived suppressor cells to form pre-metastatic niche and led to liver metastasis from colorectal cancer." (PMID 29109519, 2017). "The association between CXCL8, CXCL1 and tumor metastasis has been thoroughly described in previous studies." (PMID 28356111, 2017). "Studies have shown that CXCL1 can regulate tumor epithelial–stromal interactions that facilitate tumor growth and invasion, and CXCL1 has also been associated with angiogenesis." (PMID 27682863, 2016). "Paracrine factors, including interleukin-17, WNT16B, and CXCL1, secreted from immune cells and cancer-associated fibroblasts have been investigated as key molecules making the nearby tumor cells (so called ‘recipient cells’) more impervious to chemotherapies." (PMID 27004408, 2016). "Treatment of tumor-bearing IFN-deficient mice with recombinant murine IFN-β downregulated CXCL1 and CXCL2 expression in blood and tumor to the levels observed in control mice." (PMID 28066438, 2016). "In agreement with the effects seen in vitro, loss of COX-2 expression by tumor cells led to a significant decrease in expression of IL-6 or CXCL1 in vivo." (PMID 26343581, 2015). "CCL8 and CCL2 secreted by tumor cells were reported to recruit monocytic cells, and CXCL1 and MIF were linked to the recruitment of MDSCs." (PMID 25514599, 2015). "In summary, these data indicate a statistically significant association between stromal CXCL1 expression and tumor grade." (PMID 25344051, 2014). "CXCL1 RNA expression levels were significantly associated with tumor recurrence and decreased patient survival." (PMID 25344051, 2014). "Our studies indicate that CXCL1 is elevated in breast CAFs, and is associated with increased tumor recurrence and tumor grade." (PMID 25344051, 2014).
tumor (continued). "A recent review suggested recruitment of ASCs from ppWAT into PCa cells and the TME are precursors to tumor stromal cells and cancer‐associated fibroblasts and a source of IL‐6, TNFα, CXCL1, CXCL5, CXCL8, CXCL12, MCP‐1, and leptin facilitating tumor angiogenesis and cancer cell proliferation." (PMID 41450167, 2026). "Also, CXCL1 causes the recruitment of neutrophils into the tumor niche; these cells secrete prokineticin-2, which causes tumor cell migration and subsequent metastasis." (PMID 40427171, 2025). "Similarly, the chemokine CXCL1 is an angiogenic inflammatory marker which has been linked to neutrophil recruitment and migration of adipose stromal cells into the tumor microenvironment." (PMID 39989973, 2025). "Besides, CXCL1 expression in the tumor stroma is associated with tumor grade and recurrence, likely due to its negative regulation by TGF-β." (PMID 40909271, 2025). "In cancer, elevated CXCL1 levels have been associated with tumor cell invasion and development." (PMID 40584290, 2025). "This study reveals R. callidus as a key gut microbiota species enriched in CRC patients with high CEA levels, demonstrating its novel pro-tumor associations through positive correlations with mast cell infiltration and CXCL1 chemokine and upregulation of long-chain fatty acid metabolism." (PMID 40960294, 2025). "CXCL1 is important in the function of tumor-associated cells." (PMID 38673949, 2024). "We also demonstrated that recruitment of CXCR2+ myeloid cells to SMAD4-deficient CRCs could promote tumor invasion and metastasis, suggesting blockade of the CXCL1/8–CXCR2 axis could be a novel therapeutic approach in CRC." (PMID 38750114, 2024). "Interestingly, we also observed that squalene treatment caused a substantial decrease in expression of CXCL1 (a chemokine known to recruit target cells such as MDSCs and TAMs), in the tumor tissues." (PMID 39763673, 2024). "Furthermore, CXCL1 has been implicated in tumor formation, participating in the proliferation, differentiation, and neurogenesis of stem cells in the nervous system." (PMID 39563017, 2024). "Higher CXCL1 expression in the tumor is associated with a worse prognosis for the patient." (PMID 38673949, 2024). "CXCL1 produced by tumour-associated macrophages in malignancies could form a pre-metastatic niche to promote metastasis." (PMID 36810912, 2023). "Indirectly, CXCL1 causes the recruitment of neutrophils into the tumor niche." (PMID 37108425, 2023). "Additionally, research has demonstrated the involvement of CXCL1 in a multitude of molecular mechanisms associated with these neoplasms." (PMID 37408240, 2023). "Tumor-associated macrophages (TAM) are another source of CXCL1 in ESCC tumors." (PMID 37408240, 2023). "Tumor invasion is closely linked to the chemokines ligand 1 (CXCL1) and ligand 2 (CXCL2)." (PMID 37237548, 2023). "Additionally, in LSCC, CXCL1 is associated with the tumor–node–metastasis (TNM) stage and is inversely correlated with tumor histopathological grade." (PMID 37408240, 2023). "CXCL1 causes the recruitment of neutrophils and G-MDSCs into the tumor niche." (PMID 37408240, 2023). "Furthermore, this review discusses the association of CXCL1 with clinical aspects of gastrointestinal cancers, including its correlation with tumor size, cancer grade, tumor–node–metastasis (TNM) stage, and patient prognosis." (PMID 37408240, 2023). "CXCL1 is also important in the function of tumor-associated cells." (PMID 37108425, 2023). "For instance, the loss of SMAD4 in intestinal epithelial cells has been shown to result in the upregulation of chemotactic factors, including Ccl9, CCL15, or CXCL1/8, and thereby induces the recruitment of tumor promoting myeloid-derived cells or tumor-associated neutrophils." (PMID 37190048, 2023).
tumor (continued). "Moreover, CXCL1 signalling in the tumour microenvironment is associated with tumour progression, tumour recurrence and drug resistance; therefore, targeting CXCL1 signalling is a potential therapeutic approach for human BC." (PMID 36810912, 2023). "CXCL1 also acts on cells in the tumor niche, causing angiogenesis." (PMID 37108425, 2023). "Moreover, CXCR2-positive MDSCs are attracted to metastatic sites by CXCL1 derived from tumor-associated macrophages (TAM) due to the stimulation of VEGFA released from primary tumor cells." (PMID 35911705, 2022). "Similarly, CXCL8 is an angiogenic CXCL-type chemokine implicated in tumor microenvironment neovascularization, and a strong positive correlation was found between the chemokine and CXCL1." (PMID 36164329, 2022). "The CXCL1 secreted by tumor cells promotes tumor growth by recruiting tumor-associated neutrophils." (PMID 36275775, 2022). "In the same way, CCL2 produced by tumor cells and CSF1 produced by tumor-associated fibroblasts contribute to the generation of M2-like macrophages, and CXCL1 production by tumor cells has been linked to increased myeloid cell populations and decreased tumor infiltration of cytotoxic CD8+ T cells." (PMID 36408139, 2022). "Additionally, CXCL1 has been linked to cancer migration and invasion as well as tumour progression and poor survival in various cancer types." (PMID 35740353, 2022). "Previous research found that the tumor-associated MSCs produced chemokines Gro-α/CXCL1, Gro-β/CXCL2, and IL8, which bound to the CXCR1/2 receptor on the surface of tumor cells and led to the formation of chemoresistance and induced the polarization of macrophages." (PMID 36354566, 2022). "Furthermore, CXCL1 elevation promoted the migration of M2-tumor associated macrophages (TAMs) while disrupting the aggregation of CD4+ and CD8+ T cells at tumor sites." (PMID 36434686, 2022). "In addition, the increased expression of CXCL1 is also associated with neoangiogenesis in the tumor." (PMID 36286054, 2022). "In vivo alterations of the tumor immune environment involved fewer protumorigenic tumor-associated macrophages (TAMs) and MDSCs due to the suppression of IL-4, IL-13, and CXCL1 expression, and elevated infiltration by antitumor CTLs and NK cells attracted by elevated CXCL9 and CXCL10 levels." (PMID 35499071, 2022). "The result of the pair-t test showed that CXCL1 mRNA expression in COAD tumor tissues was markedly up-regulated than in paracancerous non-tumor colon tissues, and the diagnostic ROC curve showed that CXCL1 had a high accurately for COAD diagnosis (P<0.0001, AUC (95% Cl)=0.884(0.808-0.961) )." (PMID 34405013, 2021). "Additionally, tumor-associated LECs have been shown to upregulate CXCL1 that induced LVI in gastric cancer." (PMID 34685565, 2021). "The CXCL1 mutation induced by belinostat treatment stress might result in DNA damage in tumor cells, which causes the microenvironment to become inadaptive to tumor cell growth." (PMID 33959656, 2021). "The GRO member CXCL1 has also been implicated to recruit neutrophils in tumor mouse models." (PMID 33912188, 2021). "In addition, previous studies suggested that ITGB5 and IL18 are related to tumor invasiveness, whereas CXCL1 and SEMA4F are associated with cell proliferation." (PMID 31118022, 2019). "In addition, chemokine Cxcl1 and PD-L1 associated with immune tolerance were expressed in non-tumor tissue of the TME and correlated with the onset of macrophage and Treg infiltration as denoted by F4/80 and Foxp3 staining, respectively." (PMID 29487713, 2018). "The expression of CXCL1 in CAFs was significantly associated with tumor size." (PMID 28518141, 2017). "Accordingly, CXCL1 deficiency in tumor significantly inhibited tumor growth in vivo." (PMID 27446967, 2016).
tumor (continued). "Notably, our analysis of cytokine and chemokine transcript levels in the DTX-treated senescent tumor cells demonstrated upregulation of numerous cytokine species including those implicated in supporting tumor growth (such as CXCL1, IL-1 or IL-6)." (PMID 27448982, 2016). "In situ hybridization not only corroborated the increased expression of Cxcl1 in Stat3-deficient tumours but also identified the tumour cells as the main cellular origin of Cxcl1 as confirmed by staining for the alveolar type 2 cell-specific marker SP-C (surfactant protein C) in serial sections." (PMID 25734337, 2015). "Stable transfection of a CXCL1 expressing vector into parental Pam 212 lines recapitulated the aggressive primary tumor growth and metastatic phenotype of the metastatic variant lines, which demonstrated enhanced myeloid and monocyte leukocyte infiltration into the tumor microenvironment." (PMID 26690220, 2015). "In colorectal cancer, tumor growth in vivo is associated with increased expression of CXCL1." (PMID 24971349, 2014). "In addition, NF-κB-dependent inflammatory cytokines such as IL-6, TNF-α, and CXCL1/KC have been linked with the enhanced immunosuppressive activity of tumor-infiltrating MDSCs." (PMID 25514597, 2014). "However, we were able to analyze for associations between stromal CXCL1 RNA levels and tumor recurrence and poor survival in Oncomine using the Finak database." (PMID 25344051, 2014). "However, further subgroup univariate analysis of stage III patients indicated a significant association between higher CXCL1 expression in the tumour samples and poorer RFS (P=0.041)." (PMID 21285972, 2011). "Moreover, CXCL1 influences tumor-associated macrophages (TAM) by promoting M2 polarization." (PMID 40427171, 2025). "In addition, an increase in the concentration of KC (CXCL1), a chemokine most potently expressed by tumor-associated macrophages, and IL-5, which stimulates cell migration by activating the ERK1/2 pathway, is a characteristic feature of malignant growth and metastasis." (PMID 38891915, 2024). "Consequently, CXCL1 directly participates in the recruitment of tumor-associated neutrophils (TAN)." (PMID 38673949, 2024). "In addition, CXCL1 siRNA-mediateddownregulation of extracellular CXCL1 inhibited the formation of ECMby preventing the activation of pancreatic stellate cells and tumor-associatedfibroblasts, thus facilitating the tumor infiltration of Teff cells." (PMID 37901179, 2023). "Increased CXCL1 expression also recruits neutrophils to the metastasis site; these cells secrete growth arrest specific 6 (Gas6), a secretory factor activating the Axl receptor tyrosine kinase that causes tumor cell proliferation and thus the regrowth of the metastatic site following chemotherapy." (PMID 37408240, 2023). "The increased expression of CXCL1 in this cell plays an important role in migration and metastasis formation by stimulating the tumor cell to migrate, and causing the supporting adhesion of the tumor cell to target tissues, as well as in the recruitment of different cells in metastasis." (PMID 35054978, 2022). "Additionally, CXCL1 causes tumor cell migration, and consequently, metastasis." (PMID 35054978, 2022). "Furthermore, expression of CXCL1/2/3/9/10/11 was associated with tumor stage in CRC." (PMID 34233297, 2021). "Moreover, the expression of CXCL1/2/3/9/10/11 was associated with the tumor stage in CRC." (PMID 34233297, 2021). "Necroptosis was shown to create an immunosuppressive tumor microenvironment through the recruitment of myeloid-derived suppressor cells or tumor-associated macrophages by increasing the expression of chemokine CXCL1, which may promote tumor growth and progression." (PMID 32521727, 2020). "In addition, co-culture of gastric cancer cells and tumor-associated lymphatic endothelial cells (LECs) elevated CXCL1 secretion in LECs which in turn upregulated integrin β1 and MMP2/9 that promotes cell adhesion, migration, invasion and lymph node metastases." (PMID 33414786, 2020).